NXF1 (nuclear RNA export factor 1)
Description:
Involved in the nuclear export of mRNA species bearing retroviral constitutive transport elements (CTE) and in the export of mRNA from the nucleus to the cytoplasm (TAP/NFX1 pathway). The NXF1-NXT1 heterodimer is involved in the export of HSP70 mRNA in conjunction with ALYREF/THOC4 and THOC5 components of the TREX complex. ALYREF/THOC4-bound mRNA is thought to be transferred to the NXF1-NXT1 heterodimer for export. Also involved in nuclear export of m6A-containing mRNAs: interaction between SRSF3 and YTHDC1 facilitates m6A-containing mRNA-binding to both SRSF3 and NXF1, promoting mRNA nuclear export.
Synonyms: TAP; Mex67; DKFZp667O0311
Tractability: Small molecule: it has a binding pocket of medium quality. PROTAC: ubiquitination databases record sites on it; its protein half-life has been measured.
Gene: Protein-coding gene on chromosome 11 (62,792,123 to 62,806,302, reverse strand). Ensembl gene ENSG00000162231.
Subcellular location: Nucleus; Nucleus, nucleoplasm; Nucleus speckle; Nucleus, nuclear pore complex; Nucleus envelope; Cytoplasm; Cytoplasm, Stress granule
Subcellular location (Human Protein Atlas): Nucleoplasm
Pathways (Reactome):
Metabolism of RNA: Transport of Mature mRNA Derived from an Intronless Transcript; Transport of Mature mRNA derived from an Intron-Containing Transcript; Transport of the SLBP Dependant Mature mRNA; Transport of the SLBP independent Mature mRNA
Gene Ontology:
Molecular function: protein binding; RNA binding; mRNA binding; nucleic acid binding
Biological process: mRNA export from nucleus; poly(A)+ mRNA export from nucleus; mRNA transport
Cellular component: cytoplasm; nuclear envelope; nuclear RNA export factor complex; nuclear speck; nucleoplasm; nucleus; transcription export complex; cytosol; cytoplasmic stress granule; nuclear inclusion body; nuclear pore
Genetic constraint (gnomAD): Loss-of-function variants: 43 observed, 91.55 expected, observed/expected ratio (o/e) 0.47, 90% interval 0.37 to 0.61. The upper end of that interval is the gene's LOEUF score, 0.61, which puts it in group 2 of 6, group 1 being the genes least tolerant of losing a copy. Missense variants: 576 observed, 827.29 expected, observed/expected ratio (o/e) 0.7, 90% interval 0.65 to 0.75. Synonymous variants: 288 observed, 310.15 expected, observed/expected ratio (o/e) 0.93, 90% interval 0.84 to 1.02.
Homologues: Orthologues: chimpanzee NXF1 (100% identical), macaque NXF1 (100% identical), guinea pig NXF1 (95% identical), dog NXF1 (93% identical), pig NXF1 (92% identical), rabbit NXF1 (92% identical), rat Nxf1 (91% identical), mouse Nxf1 (91% identical), zebrafish nxf1b (63% identical), tropical clawed frog nxf1 (60% identical), zebrafish nxf1a (48% identical), Caenorhabditis elegans nxf-1 (26% identical), and 2 more. Paralogues in human: NXF2 (58% identical), NXF2B (58% identical), NXF3 (44% identical).
Diseases named in the same sentence as NXF1 in open-access papers:
NXF1 is named in the same sentence as 23 diseases in open-access papers, as found by Europe PMC text mining. Sharing a sentence is not in itself a finding about the gene and the disease. The quoted sentences say what the papers report.
virus infection (4 papers, 2018 to 2024). "We then challenged control or NXF1 knockdown S2 cells with either wild-type CrPV or mutant CrPV (they R146A) virus infection (MOI 10)." (PMID 36455064, 2022). "SFPQ was additionally identified through the siRNA screen, along with the mRNA export factor, NXF-1, as being among the strongest proviral interactors (i.e. depletion of these factors inhibited viral infection)." (PMID 34019569, 2021). "Two of these three factors, i.e., CAD and NXF1, were also remarkable insofar as all examined siRNAs targeting these factors showed a strong reduction in reporter activity following reporter virus infection." (PMID 30081931, 2018).
influenza (2 papers, 2010 to 2014). An acute viral infection of the respiratory tract, occurring in isolated cases, in epidemics, or in pandemics; it is caused by serologically different strains of viruses (influenzaviruses) designated A, B, and C, has a 3-day incubation period, and usually lasts for 3 to 10 days. "Further, select influenza mRNAs were found associated with Nxf1 in the cell, strongly supporting use of Nxf1-mediated nuclear export by these select viral mRNAs." (PMID 25168591, 2014). "RNAi screening in drosophila cells identified Nxf1 as an essential host factor for influenza mRNA nuclear export." (PMID 25168591, 2014). "Inhibition of Nxf1 resulted in less influenza intron-less mRNA export into the cytoplasm for HA and NA influenza mRNAs in both human embryonic kidney cell line (293 T) and human lung adenocarcinoma epithelial cell line (A549)." (PMID 25168591, 2014). "Here we report our results on the role of Nxf1 and Crm1 in influenza intron-less mRNA nuclear export (HA, NA, NP, PB1, PB2, and PA mRNAs)." (PMID 25168591, 2014). "We reveal a cell type difference for Nxf1-mediated nuclear export of influenza NP mRNA, a reminder that cell type can influence molecular mechanisms." (PMID 25168591, 2014). "The synthesis of influenza mRNAs by a viral polymerase and the fact that most are either intronless or contain residual introns raises the question of how, or even if, they are fed into the NXF1 pathway." (PMID 20071484, 2010). "Additional studies provide evidence of a role for host Nxf1 in export of some but not all influenza mRNAs." (PMID 25168591, 2014).
neuroblastoma (2 papers, 2013 to 2023). Neuroblastoma (NB) is the most common solid, extracranial childhood tumor. "As an example of the two opposite activities on different mRNAs, it has been shown that hippocampal FMRP protects PSD-95 mRNA from decay in an activity-dependent manner; however, FMRP protein also facilitates the decay of nuclear RNA export factor 1 (NXF1) mRNA in mouse neuroblastoma (N2a) cells." (PMID 24167470, 2013). "Among them, we focalized our attention on the proteins involved in neuroblastoma development, namely, Ubiquitin specific protease 7 (i.e., USP-7), Nuclear RNA export factor 1 (i.e., NXF1), and Pescadillo homolog (i.e., PES1)." (PMID 37298148, 2023).
acute myeloid leukemia (1 paper, 2016). Acute myeloid leukemia (AML) is a group of neoplasms arising from precursor cells committed to the myeloid cell-line differentiation. "These novel driver mutations hit histone proteins (HIST1H1D; HIST1HIC) involved in resistance to lenalidomide in multiple myeloma (IKZF3), nuclear RNA export factor 1 (NXF1) and proteins also mutated in acute myeloid leukemia and multiple myeloma (ASXL1; TRAF3)." (PMID 27580852, 2016).
Ataxia (1 paper, 2009). Ataxia refers to impaired coordination of voluntary muscle movement. "Nxf1 genotype had a highly significant impact on Atcayhes neurological phenotypes as rated by multiple observers blinded to genotype, including both reduced ataxia and complete elimination of jumps from open field behavior." (PMID 19436707, 2009).
autoimmune disease (1 paper, 2021). A disorder resulting from loss of function or tissue destruction of an organ or multiple organs, arising from humoral or cellular immune responses of the individual to their own tissue constituents. "Based on two “omics” approaches, NXF1 was identified as one of the IRF5 signaling pathway regulators, and in turn genome-wide association studies have implied the association of IRF5 with several autoimmune diseases, including SLE, Sjogren’s syndrome, inflammatory bowel disease, and MS." (PMID 34065644, 2021).
chronic lymphocytic leukemia (1 paper, 2020). "Recent studies indicate that mutation of NXF1 in mice can lead to disruptions in hematopoiesis in a lineage-specific manner, and NXF1 has been found to be mutated in chronic lymphocytic leukemia (CLL) patients." (PMID 33375634, 2020).
fragile X syndrome (1 paper, 2009). A genetic syndrome caused by mutations in the FMR1 gene which is responsible for the expression of the fragile X mental retardation 1 protein. "Nxf1 expression is tightly controlled, as it has been shown to be crucially involved in the normal development of both male neurons and germ cells in cases of Fragile X syndrome." (PMID 19127293, 2009).
glioblastoma (1 paper, 2012). The most malignant astrocytic tumor (WHO grade IV). "Furthermore, miR-149 is also downregulated in glioblastoma cells and has been proposed to act as a tumor suppressor by targeting RAP1B, CD47, CCN1, and NXF1." (PMID 23144691, 2012).
lung adenocarcinoma (1 paper, 2014). A carcinoma that arises from the lung and is characterized by the presence of malignant glandular epithelial cells. "This led us to conclude there is a cell type difference in Nxf1-mediated NP mRNA nuclear export: in human lung adenocarcinoma epithelial cell line (A549) NP mRNA nuclear export is Nxf1-mediated while in human embryonic kidney cell line (293 T) NP mRNA nuclear export is Nxf1 independent." (PMID 25168591, 2014).
lung carcinoma (1 paper, 2021). "It is possible that overexpression of TPR in lung cancer cells causes mislocalization of its interaction partners such as NXF1, leading to dysregulated nuclear export of RNAs and proteins related to cancer development." (PMID 34793452, 2021). "The viability and proliferation capacity of lung cancer cells were dramatically reduced when NXF1 was knocked down, similar to the effects of TPR knockdown." (PMID 34793452, 2021). "Here, we demonstrated that NXF1 binds tRNAs in human lung cancer cells and mediates tRNA nuclear export." (PMID 34793452, 2021). "This implies that NXF1 plays a less dominant role than TPR in the tumorigenesis of lung cancer." (PMID 34793452, 2021). "Our finding of their functions in tRNA trafficking in lung cancer cells suggests that TPR and NXF1 orchestrate the nuclear export of different forms of RNAs to promote protein synthesis." (PMID 34793452, 2021). "To test whether NXF1 and XPO1 are exporters of tRNAs in lung cancer cells, we performed RNA immunoprecipitation (RIP) with NXF1 and XPO1 antibodies respectively." (PMID 34793452, 2021). "Notably, our analysis of lung cancer patient samples showed significantly higher expression of TPR in tumor than in adjacent tissues, whereas NXF1 remained unchanged." (PMID 34793452, 2021). "However, unlike TPR, the mRNA and protein level of NXF1 was not increased in tumor tissues from lung cancer patients, and knockdown of TPR did not down-regulate the expression of NXF1." (PMID 34793452, 2021).
male infertility (1 paper, 2025). The inability of the male to effect fertilization of an ovum after a specified period of unprotected intercourse. "The study introduces NXT2 as a candidate gene for male infertility and shows that the encoded protein is involved in RNA nucleocytoplasmic transport in human testis by interacting with the RNA export factor NXF1 and proteins of the nuclear pore complex." (PMID 40624043, 2025). "In summary, we introduce NXT2 as a strong candidate gene for male infertility and demonstrate that the encoded protein is one key player in adult human testis bulk RNA nucleocytoplasmic transport by interacting with the RNA export factor NXF1 and proteins of the nuclear pore complex." (PMID 40624043, 2025).
prostate carcinoma (1 paper, 2021). A carcinoma that arises from epithelial cells of the prostate gland. "Some researchers analyzed the important m6A RNA regulators, which act as prognosis factors in prostate cancer, and identified RBMX, NXF1, YTHDF1, HNRNPA2B1, and TRMT112 as critical genes that have great effects on the prognosis of PCa patients." (PMID 34899855, 2021).
infection (11 papers, 2008 to 2024). The state of being infected such as from the introduction of a foreign agent such as serum, vaccine, antigenic substance or organism. "Loss of hnRNP UL1 reduced viral gene expression during infection for all strains, as did our control target NXF1." (PMID 36542656, 2022). "This alternative model of pgRNA encapsidation would occur in the early phases of infection, to the contrary of the late phase, when pgRNA export is NXF1-dependent." (PMID 38005895, 2023). "In our view, nsp1-sensitive transcripts correspond to transcriptionally active loci at the time of infection that are blocked by the interaction of nsp1 with NXF1." (PMID 36435849, 2022). "By contrast, in NXF1 KD cells, both wild-type and mutant CrPV (R146A) infection resulted in ~three-fold increase in viral titer." (PMID 36455064, 2022). "Using these screening conditions, more than 80% of siScr-transfected cells were infected, while cells transfected with siRNAs against either CSE1L (siCSE1L) or NXF1 (siNXF1) inhibited infection by more than 85%." (PMID 28272419, 2017). "Here we inhibited Nxf1 and Crm1 nuclear export prior to infection with influenza A/Udorn/307/1972(H3N2) virus and analyzed influenza intron-less mRNAs using cellular fractionation and reverse transcription - quantitative polymerase chain reaction (RT-qPCR)." (PMID 25168591, 2014). "Similar results were demonstrated upon overexpression of NXF1 or TPR, which connects viral mRNA to the nuclear pore complex, further demonstrating that nuclear export is a limiting step during infection." (PMID 36542656, 2022). "We have tested the interaction between NS1-BP and key members of the mRNA nuclear export machinery and found that NS1-BP interacts with the mRNA export receptor NXF1 in the presence or absence of infection." (PMID 39384042, 2024). "In these studies involving NXF1 and viral RNAs, the key experimental approaches employed siRNA knockdown of NXF1 and/or protein-RNA binding assays without chemical cross-linking of NXF1 to viral mRNAs upon infection." (PMID 23872491, 2013). "Again, we found that NS1-BP also binds NXF1 in the absence of infection." (PMID 39384042, 2024). "Interestingly, mutant n504, which also does not interact with TAP/NXF1 was confined to the nucleus at 6 h after infection, however, Hsc70 foci were seen to form." (PMID 18231578, 2008). "In contrast to NXF1, CEACAM6 is not directly involved in steps of RNA synthesis but seems to interact with newly synthesized viral NA proteins during infection, which activates the Src/Akt survival pathway in A549 cells as shown by Gaur and colleagues." (PMID 30973879, 2019).
cancer (5 papers, 2020 to 2025). A tumor composed of atypical neoplastic, often pleomorphic cells that invade other tissues. "hnRNPA2B1 selectively facilitates the nuclear export of m6A-modified mRNAs by interacting with the Aly/REF export factor (ALYREF)-nuclear RNA export factor 1 (NXF1) complex, thereby enhancing the expression of stemness-related genes critical for cancer stem cell maintenance." (PMID 40986143, 2025). "The identification of core proteins NXF1 and NCBP2 as driver genes in this pathway provides new avenues for exploring the functional implications of the ubiquitin-proteasome system in cancer." (PMID 40522954, 2025). "Similarly, the core proteins of NXF1 and NCBP2 in the Ubiquitin Mediated Proteolysis pathway, and RPS27A as a core protein in RNA Translation pathway, were also drive genes of the two cancers." (PMID 40522954, 2025). "Pitifully, the link between NXF1 and any cancer has not been established." (PMID 33343639, 2020).
tumor (3 papers, 2011 to 2021). "Instead, approximately 40% and 65% of the tumor samples showed a lower staining than the normal tissues in the UAP56 and NXF1 IHC reports respectively." (PMID 21329510, 2011).
NXF1 also shares sentences with these, for which no sentence is quoted: malaria (2 papers); breast carcinoma (1); COVID-19 (1); inflammatory bowel disease (1); liver cancer (1); multiple myeloma (1); Sjogren syndrome (1).